FAM153A (family with sequence similarity 153 member A)
Synonyms: NY-REN-7
Tractability: No criterion of Open Targets' tractability assessment is met for any kind of drug.
Gene: Protein-coding gene on chromosome 5 (177,707,981 to 177,784,435, reverse strand). Ensembl gene ENSG00000170074.
Gene Ontology:
Molecular function: protein binding
Genetic constraint (gnomAD): Loss-of-function variants: 6 observed, 10.49 expected, observed/expected ratio (o/e) 0.57, 90% interval 0.31 to 1.13. The synonymous counts are far from expectation, so gnomAD's model fits this gene poorly and the ratio says little. Missense variants: 40 observed, 111.83 expected, observed/expected ratio (o/e) 0.36, 90% interval 0.28 to 0.47. Synonymous variants: 17 observed, 34.99 expected, observed/expected ratio (o/e) 0.49, 90% interval 0.33 to 0.73.
Diseases named in the same sentence as FAM153A in open-access papers:
FAM153A is named in the same sentence as 1 disease in open-access papers, as found by Europe PMC text mining. Sharing a sentence is not in itself a finding about the gene and the disease. The quoted sentences say what the papers report.
Obesity (1 paper, 2023). Accumulation of substantial excess body fat. "BMP3 is associated with preadipocyte proliferation, FAM153A is a yet-to-be characterized protein of human adipocytes, and GRB7 is associated with human obesity." (PMID 38069028, 2023).